H19 (H19 imprinted maternally expressed transcript)
Diseases named in the same sentence as H19 in open-access papers (continued):
Sharing a sentence is not in itself a finding about the gene and the disease.
gastric cancer (continued). "Arita and colleagues found that circulating LncRNA H19 level is increased patients with gastric cancer when compared with healthy subjects and reduced after surgery, suggesting that LncRNA H19 might be a new potential biomarker for diagnosis of gastric cancer." (PMID 26221732, 2015). "Furthermore, plasma levels of HULC were increased in hepatocellular carcinoma, H19 in gastric cancer, and MALAT-1 in prostate cancer patients." (PMID 25685243, 2015). "Furthermore, over-expression of H19 contributes to the proliferation, migration, invasion and metastasis of gastric cancer." (PMID 25928635, 2015). "Indeed, H19 overexpression is often correlated with poor prognosis in bladder, lung, oesophageal and gastric cancers." (PMID 26353930, 2015). "Likewise, H19 can function as a primary microRNA precursor and H19-derived miR-675 increases cell proliferation in gastric cancer cells by targeting the tumor suppressor RUNX1." (PMID 26379360, 2015). "miR-675, along with its precursor long non-coding RNA H19, was found to inhibit invasion and metastasis in hepatocellular carcinomas, but was shown to promote the pathogenesis and metastasis of gastric cancer and target the tumor suppressor retinoblastoma in colorectal cancer." (PMID 26472042, 2015). "Comparing with respective normal cell line, H19 was found highly expressed in stomach cancer cell lines (AGS, MGC-803 and SGC-7901) and hepatocellular carcinoma cell lines (SMMC-7721 and HepG2), while lowly expressed in lung cancer cell line (A549) and prostate cancer cell lines (Du-145 and PC-3)." (PMID 24063685, 2013). "The overexpression of H19 in gastric cancer cell lines and tissues suggests that H19 may be participated in gastric cancer." (PMID 24063685, 2013). "Since H19 was found the most up-regulated lncRNA in gastric cancer tissue, up to 8.91-fold change in microarray detection, to validate this result, we detected the expression level of H19 in two types of cancer tissues, biopsy tissues and surgical specimens, by qRT-PCR." (PMID 24063685, 2013). "The overexpression of H19 in gastric cancer suggests that H19 may be participated in gastric cancer." (PMID 24063685, 2013). "Together with the increased expression of H19 in gastric cancer cell lines, we suggest that H19 may play an important role in gastric cancer pathogenesis." (PMID 24063685, 2013). "First, we explored the expression level of H19 in 15 pairs of gastric carcinoma’ biopsy tissues." (PMID 24063685, 2013). "Moreover, it has been found that ectopic expression of H19 increased cell proliferation, whereas H19 silencing (siRNAs) contributed to apoptosis in human gastric cancer cells (AGS cells)." (PMID 23222637, 2012). "This is the first study to detect on the LOI of LIT1, IGF2 and H19 in gastric cancer in China-Mainland patients and LOI of IGF2 positive correlation with gastric corpus tumour (OR = 8, 95%CI = 1.425-44.920, p = 0.018) and lymph node metastasis (OR = 4.5, 95%CI = 1.084-18.689, p = 0.038)." (PMID 19737423, 2009). "For example, lncRNA H19, which is abnormally expressed in gastric cancer, influences the infiltration of cancer-associated fibroblasts (CAFs), macrophages, CD4+T cells, and CD8+T cells in the TME through the miR-378a-5p/SERPINH1 axis, thereby promoting the progression of gastric cancer." (PMID 41229433, 2025). "H19 is overexpressed in gastric cancer (GC) cells and contributes to immune escape from GC cells by decreasing immune cell activity and IL-2 expression through the miR-519d-3p/LDHA/lactate axis." (PMID 38715092, 2024). "Both these suggest that H19 could be a prognostic value lncRNA in gastric cancer." (PMID 34977037, 2021). "In addition, another research showed serum H19 lncRNA was upregulated in gastric cancer." (PMID 31619233, 2019).
gastric cancer (continued). "Additionally, H19 is correlated with poor prognosis and is upregulated in gastric cancer." (PMID 27911863, 2017). "Aberrant alterations of H19 expression have been demonstrated in various tumors, including gastric cancer (GC), implicating a crucial role of H19 in cancer progression." (PMID 28230721, 2017). "Indeed, HOTAIR, HULC and H19 expression levels in plasma have been demonstrated to correlate with outcome in series of patients with metastatic colon cancer, hepatocellular carcinoma and gastric cancer, respectively." (PMID 27340923, 2016). "Thus H19/miR-675 regulates the expression of RUNX1 to modulate gastric cancer." (PMID 27163185, 2016). "In this study LIT1, IGF2 and H19 imprinting status in gastric cancer (GC) which is the second most common cause of cancer-related death in the world was investigated and whether LOI of LIT1, IGF2 and H19 are associated with clinicopathological features was evaluated." (PMID 19737423, 2009). "One study showed that H19 effectively recruited the m6A reader YTHDF1, which significantly promoted the translation of SCARB1 and facilitated angiogenesis, specifically in gastric cancer." (PMID 38965575, 2024). "Some typical "microRNA sponges" such as H19 30, PRKCA-AS1 31, HOTAIR 32 and XIST 33 have been involved in regulating tumor progression in nasopharyngeal carcinoma, uveal melanoma and gastric cancer." (PMID 38370382, 2024). "The RNA pulldown assay showed that the lncRNA H19 binds to miR-361, miR-519a, miR-541a, miR-516b, and miR-193a in the MKN-45 gastric cancer cell line." (PMID 36090894, 2022). "Another study demonstrated that ISM1 is a binding protein of lncRNA H19, which mediates ISM1 upregulation and boosts carcinogenesis and metastasis of gastric cancer." (PMID 36611811, 2022). "Research studies have discovered that the expression of lncRNAs, including MALAT1, H19, MEG3, and TUSC7, markedly control gastric cancer cell migration, proliferation, invasion, metastasis, cell cycle, tumorigenicity, and apoptosis." (PMID 36110523, 2022). "Some identified oncogenic lncRNAs overexpressed in gastric cancerous tissue, such as H19, HOTAIR, and MALAT1, whereas others are expressed in the tissue from gastric carcinoma at a low level, such as LincRNA-p21, LINC00261, CTLSP4 and SPRY4-IT1." (PMID 36310592, 2022). "Moreover, researchers examined H19 expression levels in 12 pairs of fresh gastric cancer tissues and corresponding normal adjacent tissues, and the RT–qPCR results indicated that H19 was more highly expressed in gastric cancer tissues than in corresponding normal adjacent tissues." (PMID 34977037, 2021). "Of note, the promoting effect of H19 and SNHG11 on EMT have been validated in gastric cancer, hepatocellular cancer, and glioma." (PMID 34880375, 2021). "It has been reported that HOTAIR, ANRIL, GAPLINC, GHET1, H19, GAS5, and FENDRR, etc., play roles in the malignant progression of gastric cancer." (PMID 33744848, 2021). "Only 6 (H19, HCP5, LINC00511, MALAT1, OIP5-AS1 and RP11-618G20.1) out of 79 lncRNAs were significantly up-regulated in gastric cancer tissues compared to normal controls." (PMID 32742441, 2020). "Specifically, inhibition of lncRNA H19 and lncRNA PVT1 expression can effectively inhibit the cancerization, metastasis, and angiogenesis of gastric cancer." (PMID 33680956, 2020). "Also, in plasma of preoperative patients with gastric cancer (GC), the H19 plasma levels were higher than that of healthy controls." (PMID 31827510, 2019). "The knockdown of H19 inhibits the growth of HCC and gastric cancer cells under hypoxic recovery conditions." (PMID 30890582, 2019). "In accordance with the previous studies, lncRNA H19 and lncRNA HOTAIR were up-regulated and LINC00261 was down-regulated in stomach cancer." (PMID 28484081, 2017).
gastric cancer (continued). "The situations in gastric cancer are sketched by tumor suppressor candidate 7 (TUSC7)/miR-23b, H19/miR-141, and maternally expressed 3 (MEG3)/miR-141." (PMID 26788991, 2016). "For example, lncRNA GAS5 can function as a ceRNA for miR-21; long non-coding RNA H19 promotes glioma cell invasion by deriving miR-675; Long non-coding RNA MEG3 functions as a competing endogenous RNA of miR-181 s to regulate gastric cancer progression." (PMID 27620004, 2016). "The most down-regulated lncRNAs in gastric cancer tissues were FER1L4, uc001lsz, BG491697, AF131784, uc009ycs, BG981369, AF147447, HMlincRNA1600, and AK054588; while the most up-regulated ones were H19, HMlincRNA717, BM709340, BQ213083, AK054978, and DB077273." (PMID 24063685, 2013). "Consequently, H19 plays a regulatory role in gastric cancer (GC) angiogenesis through the YTHDF1/SCARB1 axis, offering additional insights into the mechanism underlying HIF‐1α/H19/YTHDF1/SCARB1 regulation in GC angiogenesis." (PMID 39135292, 2024). "Moreover, it has been reported that H19 activates NF-κB via TAK1 phosphorylation and promotes gastric cancer cell growth via NF-κB activation." (PMID 36110523, 2022). "H19 is involved in the invasion, migration, epithelial-mesenchymal transition (EMT), and metastasis of various cancers, such as hepatic cancer, pancreatic cancer, and gastric cancer." (PMID 35571069, 2022). "Similarly, lncRNAs, such as H19, TINCR, AOC4P, BANCR, LINC00857, and CCAT2, are detectable in body fluids and can be used to efficiently differentiate gastric cancer patients from healthy controls." (PMID 34885213, 2021). "Yang and colleagues suggested that serum H19 and LINC00152 might be potential biomarkers for diagnosis of gastric cancer." (PMID 29088878, 2017). "Recent data indicate that H19-derived miR-675 favours tumor progression by repressing the expression of several target genes, including Rb in colorectal cancer, Twist1 in hepatocellular carcinoma, and RUNX1 in gastric cancer." (PMID 26353930, 2015). "In our previous report, the fold change (FC) of H19 in 74 gastric cancer versus paired noncancerous tissues was 6.015, with a P-value of 0.017." (PMID 25928635, 2015). "We previously showed that the expression of lncRNA H19 (H19) was higher in gastric cancer (GC) tissues than that in paired noncanerous tissues." (PMID 24810858, 2014). "The expression level of H19 in gastric cancer tissues was found to be evidently higher than that in non-tumor tissues." (PMID 24063685, 2013). "We further analyzed in gastric cancer subtypes the expression of genes involved in epigenetic controls, such as EZH2 (Enhancer of zest homolog 2 involved in histone modifications), non-coding RNA (including long non-coding RNAs such as HOTAIR, H19) and DNMT1 (involved in DNA methylation)." (PMID 40868070, 2025). "However, the molecular mechanism of H19 regulating gastric cancer has not been elucidated in detail." (PMID 37821504, 2023). "As H19 was reported to be the upstream member of the NF-κB pathway upon TNF-α stimulation, we speculated that H19 might play an essential role in TP/TNF-α–induced apoptosis in gastric cancer cells." (PMID 36110523, 2022). "Increased lncRNA H19 expression induces bortezomib resistance in multiple myeloma by upregulating MCL-1 via sponging miR-29b-3p LncR-D63785 acts as a competitive endogenous RNA of miR-422a and promotes chemotherapy resistance by blocking miR-422-dependent suppression of MEF2D in gastric cancer." (PMID 31581131, 2019). "However, the relationship between H19 and pgk1 in gastric cancer has not yet been reported." (PMID 37821504, 2023).
gastric cancer (continued). "H19 sponges miR-223p to enhance Snail expression and EMT process in gastric cancer while combined detections of H19, MEG3 and miR-675-5p have been demonstrated to effectively distinguish gastric cancer from non-tumor samples with a specificity or sensitivity of > 85% in the clinic." (PMID 32272875, 2020).
bladder cancer (160 papers, 2000 to 2025). "Treatment of bladder cancer cells with exosomes isolated from tumor-associated macrophages enhances H19 expression and autophagic response." (PMID 36685879, 2022). "H19 also increases bladder cancer metastasis by associating with EZH2 and inhibiting E-cadherin expression." (PMID 36578923, 2022). "Taken together, these data demonstrated that the association of H19 upregulation with EZH2 increased bladder cancer metastasis by inhibiting Wnt/β-catenin-mediated E-cad expression." (PMID 34977037, 2021). "Serum exosomal H19 is identified as a potentially diagnostic and prognostic biomarker in bladder cancer." (PMID 33949761, 2021). "Recently, another study revealed that YAP1-enhanced H19 overexpression was associated with poorer clinicopathological prognoses of bladder cancer patients." (PMID 34421359, 2021). "H19, as the first discovered lncRNA, was found in the 1980s, and the association between its polymorphism and bladder cancer was identified in 2008." (PMID 32878251, 2020). "Other studies examining lncRNA H19 polymorphisms and the risk of bladder cancer in the Chinese population have suggested the H19 that rs217727 polymorphism is associated with an elevated risk of bladder cancer." (PMID 31013794, 2019). "Another study focused on polymorphisms in the H19 gene and the risk of bladder cancer in 177 patients with bladder cancer in the Netherlands." (PMID 31013794, 2019). "Studies have suggested that the re-expressed H19 gene in bladder cancer is associated with a higher risk of recurrent disease." (PMID 31013794, 2019). "Although a similar relationship between H19 and Id2 has been indicated previously in bladder cancer cells and acute myelocytic leukemia cells, the underlying mechanistic relationship between them have not been well investigated." (PMID 31170091, 2019). "H19 has been reported to enhance bladder cancer metastasis by associating with EZH2 and inhibiting E-cad expression." (PMID 30517191, 2018). "Such as, long non-coding RNA H19 increased bladder cancer metastasis by associating with EZH2 and inhibiting E-cadherin expression." (PMID 29113337, 2017). "A previous study reported that lncRNA H19 suppressed the expression of the target gene by associating with EZH2 in bladder cancer." (PMID 27845892, 2016). "Decreased DNA methylation at the IGF2/H19 DMR has been associated with reduced IGF2 expression in bladder cancer." (PMID 26115033, 2016). "H19 increases bladder cancer metastasis by associating with EZH2, which increases Wnt/β-catenin activation and results in a decreased expression of E-cadherin." (PMID 27613832, 2016). "It has been known that H19 is a potent oncogene, and it is associated with tumorigenesis, metastasis and poor prognosis of bladder cancer." (PMID 27363013, 2016). "In urinary system tumors, there have been reports in recent years about lncRNA H19 associating with bladder cancer." (PMID 26055877, 2015). "Upregulated H19 also increases bladder cancer cell metastasis by associating EZH2 and inhibiting E-cad expression." (PMID 24069260, 2013). "The knocking-down of H19 message again caused a very significant retardation of tumor growth of the human bladder carcinoma cell line UMUC3 in vivo, as compared to control which was in vitro-transfected with GFP siRNA." (PMID 17786216, 2007). "For instance, Urothelial Cancer Associated 1 (UCA1) is a well-documented lncRNA in bladder cancer that promotes tumorigenic potential and drug resistance, and H19 RNA levels are found to be much higher in both primary and metastatic tumor than in normal tissues." (PMID 38846969, 2024). "On the other hand, the LncRNA H19 SNP rs2839698 was related to the lower risk of bladder cancer." (PMID 33799753, 2021). "The detection of serum exosomal H19 could thus be used as a new non-invasive diagnostic and prognostic biomarker for bladder cancer patients." (PMID 33291403, 2020).